RAB3B (RAB3B, member RAS oncogene family)
Description:
The small GTPases Rab are key regulators of intracellular membrane trafficking, from the formation of transport vesicles to their fusion with membranes. Rabs cycle between an inactive GDP-bound form and an active GTP-bound form that is able to recruit to membranes different sets of downstream effectors directly responsible for vesicle formation, movement, tethering and fusion.
Tractability: Small molecule: a structure with a bound ligand is known. Antibody: UniProt places it where antibodies can reach, with high confidence; its Gene Ontology location is reachable by antibodies, with medium confidence. PROTAC: ubiquitination databases record sites on it; its protein half-life has been measured.
Gene: Protein-coding gene on chromosome 1 (51,907,956 to 51,990,700, reverse strand). Ensembl gene ENSG00000169213.
Subcellular location: Cell membrane; Golgi apparatus
Subcellular location (Human Protein Atlas): Cell Junctions
Pathways (Reactome):
Metabolism of proteins: RAB geranylgeranylation
Gene Ontology:
Molecular function: G protein activity; GDP binding; GTPase activity; myosin V binding; protein binding; GTP binding; GTP-dependent protein binding
Biological process: antigen processing and presentation; positive regulation of dopamine uptake involved in synaptic transmission; regulation of synaptic vesicle cycle; regulation of vesicle size; exocytosis
Cellular component: cytoplasm; dopaminergic synapse; extracellular exosome; perinuclear region of cytoplasm; synaptic vesicle membrane; vesicle; endosome; Golgi apparatus; plasma membrane; synaptic vesicle; secretory granule
Genetic constraint (gnomAD): Loss-of-function variants: 9 observed, 18.48 expected, observed/expected ratio (o/e) 0.49, 90% interval 0.29 to 0.85. The upper end of that interval is the gene's LOEUF score, 0.85, which puts it in group 3 of 6, group 1 being the genes least tolerant of losing a copy. Missense variants: 221 observed, 289.14 expected, observed/expected ratio (o/e) 0.76, 90% interval 0.68 to 0.85. Synonymous variants: 99 observed, 110.48 expected, observed/expected ratio (o/e) 0.9, 90% interval 0.76 to 1.06.
Homologues: Orthologues: chimpanzee RAB3B (99% identical), macaque RAB3B (99% identical), rabbit RAB3B (99% identical), pig RAB3B (98% identical), mouse Rab3b (97% identical), dog RAB3B (97% identical), guinea pig RAB3B (96% identical), rat Rab3b (96% identical), tropical clawed frog rab3b (82% identical), zebrafish rab3b (80% identical). Paralogues in human: RAB3C (81% identical), RAB3A (78% identical), RAB3D (76% identical), RAB10 (45% identical), RAB8A (45% identical), RAB13 (44% identical), RAB8B (43% identical), RAB1A (42% identical), RAB1B (41% identical), RAB35 (41% identical), RAB12 (40% identical), RAB26 (40% identical), and 56 more.
Diseases named in the same sentence as RAB3B in open-access papers:
RAB3B is named in the same sentence as 47 diseases in open-access papers, as found by Europe PMC text mining. Sharing a sentence is not in itself a finding about the gene and the disease. The quoted sentences say what the papers report.
prostate carcinoma (6 papers, 2014 to 2024). A carcinoma that arises from epithelial cells of the prostate gland. "Several previous studies have reported the involvement of Rab3B in hepatocellular carcinoma, glioma, breast cancer, and prostate cancer." (PMID 38834947, 2024). "RAB3B expression is elevated in patients with prostate cancer and is an important regulator of cancer progression." (PMID 35664777, 2022). "RAB3B, has been shown to be overexpressed in prostate cancer patients and promote prostate cancer cell survival." (PMID 32821544, 2020). "RAB3B, up-regulated in prostate cancer through AR, was the top-most jointly differentially expressed gene in this subgroup, with reduced expression relative to either NEPCs or adenocarcinomas." (PMID 29132337, 2017). "Rab3B can regulate breast cancer cell proliferation and invasion and prostate cancer cell survival." (PMID 38834947, 2024). "Moreover, research has additionally discovered that RAB3B is excessively expressed in gliomas, prostate carcinoma, lung adenocarcinoma, and gastric carcinoma." (PMID 38688977, 2024). "Additionally, studies have found that RAB3B can act as a hub gene in the diagnosis and prognosis prediction of lung adenocarcinoma, glioma, prostate cancer, gastric cancer, and colorectal cancer." (PMID 38688977, 2024). "Among them, up-regulation of Rab3B is reported in prostate cancer, promoting cancer cell survival." (PMID 24447584, 2014). "In addition, Rab3B upregulation contributes to prostate cancer cell survival." (PMID 38834947, 2024).
glioma (4 papers, 2022 to 2025). A benign or malignant brain and spinal cord tumor that arises from glial cells (astrocytes, oligodendrocytes, ependymal cells). "However, in addition to being a potential target for CAR-T Cell therapies, the expression levels of RAB3B influence the progression of gliomas, metastasis and chemoresistance in cancer stem-like sphere cells from a human hepatoma cell line." (PMID 39736966, 2025). "Additionally, the inhibition of RAB3B greatly impeded cell proliferation in gliomas by halting the cell cycle and triggering apoptosis." (PMID 38688977, 2024). "In glioma, Rab3B is also upregulated and has a prognostic significance." (PMID 38834947, 2024). "RAB3B knockdown inhibits proliferation and promotes apoptosis of glioma cells." (PMID 35664777, 2022). "RAB3B expression was higher in glioma tissues, which correlated with the grade of glioma." (PMID 35664777, 2022).
breast carcinoma (3 papers, 2014 to 2024). "Over-expression of miR-200b or knock-down of RAB21, RAB23, RAB18 and RAB3B inhibited breast cancer cell proliferation and invasion in vitro." (PMID 24447584, 2014). "In our study, we identified RAB21, RAB23, RAB18 and RAB3B as novel direct targets of miR-200b in breast cancers." (PMID 24447584, 2014). "The expressions of RAB21, RAB23, RAB18 and RAB3B were suppressed by transfection of miR-200b in breast cancer cells." (PMID 24447584, 2014). "Transfection of siRNAs for RAB21, RAB23, RAB18 and RAB3B also inhibits breast cancer cell proliferation and invasion." (PMID 24447584, 2014). "The regulations of RAB21, RAB23, RAB18 and RAB3B by miR-200b were further confirmed in breast cancer cell lines." (PMID 24447584, 2014). "Knockdown of Rab3B leads to reduced proliferation and invasion in breast cancer cells." (PMID 38834947, 2024). "Members of RAB family, RAB21, RAB23, RAB18 and RAB3B were novel targets regulated by miR-200b in breast cancer, which could be of promising therapeutic significance." (PMID 24447584, 2014).
gastric cancer (3 papers, 2021 to 2024). A primary or metastatic malignant neoplasm involving the stomach. "Since DDX6 plays an oncogenic role in multiple cancers including gastric cancer, colon cancer, and myeloid leukemia, we focused on the interaction between Rab3B and DDX6." (PMID 38834947, 2024). "A negative correlation was found between VSTM2L and CIMP, and a CIMP-related gene signature comprising six genes (VSTM2L, CST6, SLC7A2, RAB3B, IGFBP1, and EVX2) stratified gastric cancer patients into high‐ and low-risk groups with distinct prognoses." (PMID 35155565, 2021).
hepatoma (3 papers, 2022 to 2025). "RAB3B might be crucial in the secretion of extracellular vesicles, such as exosomes, and might regulate the expression of related genes; hence, further detailed investigations on cell–cell communication would disclose key genes that can be targeted for the therapy of hepatoma." (PMID 35277124, 2022).
chordoma (2 papers, 2010 to 2025). Chordomas are rare malignant tumors arising from embryonic remnants of the notochord in axial skeleton. "By knocking down of the enhancer and chromatin accessibility regions in RAB3B (chr1: 51955000–51965000), we found the decreased expression of RAB3B in mRNA and protein levels, indicating the enhancer‐associated RAB3B transcriptional activation in chordoma." (PMID 40135815, 2025). "Here, via transcriptome and proteome analyses, RAB3B is unveiled as a prominent oncogenic regulator in chordoma, with high expression and enhancer‐associated transcriptional activity." (PMID 40135815, 2025). "In this study, we found that RAB3B‐mediated mTORC1 signaling is tightly associated with chordoma cell proliferation, migration, and tumorigenicity, which may explain the clinical application of mTORC1‐targeted therapy in chordoma patients." (PMID 40135815, 2025). "Next, we explored the effects of RAB3B knockdown on sphere formation and found knockdown of RAB3B significantly constrained the tumorsphere formation in chordoma cells." (PMID 40135815, 2025). "We further sought to determine the predictive value of RAB3B/S6 axis in the prognostic evaluation and mTORC1 inhibitor response in chordoma patients." (PMID 40135815, 2025). "In view of the tumorigenic roles of RAB3B in chordoma and above‐mentioned regulation of RAB3B/DUSP12 in mTORC1 signaling, we further explored the roles of DUSP12 in the stemness and tumorigenesis of chordoma." (PMID 40135815, 2025). "Pharmacological targeting mTORC1 pathway dramatically impeded the RAB3B‐induced stemness regulation, protein translation, and chordoma tumorigenicity, while RAB3B knockdown desensitized mTORC1 inhibition." (PMID 40135815, 2025). "This approach enables therapeutic potentials of mTORC1‐targeted therapy for advanced chordoma patients with aberrant RAB3B/p‐S6 hyperactivation." (PMID 40135815, 2025). "Our findings also highlight that RAB3B overexpression drives oncogenesis of chordoma and renders chordoma patients prone to mTORC1‐targeted therapy." (PMID 40135815, 2025). "In the current study, we identified RAB3B as a novel oncogenic regulator of chordoma, playing crucial roles in chordoma cell tumorigenicity and prognosis prediction." (PMID 40135815, 2025). "As for protein levels, we found the overexpression of RAB3B in chordoma, coupled with its low expression in embryonic NP." (PMID 40135815, 2025). "In the RAB3B‐small‐interfering RNA (siRNA)‐treated chordoma cells, mRNA and protein levels of chordoma stemness markers (TBXT, NANOG, OCT4, and SOX2) were significantly decreased." (PMID 40135815, 2025). "Through determining the RAB3B‐mediated program in chordoma, it is identified that it enhanced the phosphorylation of S6 specifically at S235/236 and directly bound to S6." (PMID 40135815, 2025). "Based on the transcriptomic data of clinical chordoma tissues, RAB3B showed a high correlation with stemness markers, such as TBXT (R = 0.85, p = 5e–15), OCT4 (R = 0.5, p = 0.00016) and NANOG (R = 0.41, p = 0.0027)." (PMID 40135815, 2025). "Compared with embryonic and peritumoral NP, the mRNA levels of RAB3B were significantly higher in chordoma." (PMID 40135815, 2025). "The results revealed more and consistent peaks in the region of RAB3B, implicating high transcriptional activity of RAB3B in chordoma related to enhancers." (PMID 40135815, 2025). "Via immunofluorescence, colocalization between S6 and RAB3B was also observed in chordoma cell lines, such as CH22 and U‐CH2 cells." (PMID 40135815, 2025). "Based on our transcriptomic data of chordoma samples, we investigated the correlation between RAB3B and key markers of mTORC1 signaling." (PMID 40135815, 2025). "The results revealed that high levels of RAB3B, as well as Nanog, Oct4, Sox2, and Brachyury, were verified in the sphere formation assays of chordoma cell lines." (PMID 40135815, 2025).
chordoma (continued). "More peaks were found in the region of RAB3B in chordoma cell lines, indicating its high transcriptional activity in chordoma." (PMID 40135815, 2025). "To further determine the role of RAB3B in predicting response to mTORC1 inhibitors in chordoma patients, we retrospectively collected advanced chordoma cases with the treatment of targeted therapies." (PMID 40135815, 2025). "The heatmap revealed that MIR5690, SNORD15B, RAB3B were highly expressed in chordoma, along with the generally reported chordoma regulators, such as KRT19, LYST, and EGFR." (PMID 40135815, 2025). "The combination of RAB3B and p‐S6 indicates a good prognostic value and predicts mTORC1 inhibitors response for chordoma patients." (PMID 40135815, 2025). "In clinic, the combination of RAB3B and p‐S6 suggested a good prognostic value and predicted mTORC1 inhibitors response for chordoma patients." (PMID 40135815, 2025). "Moreover, based on in vitro experiment and clinical chordoma case, RAB3B was identified as a predictor for response to mTORC1‐targeted therapy in chordoma." (PMID 40135815, 2025). "The chordoma stemness and tumorigenic functions of RAB3B were further evaluated in chordoma." (PMID 40135815, 2025). "Next, we explored what induced the high expression of RAB3B in chordoma." (PMID 40135815, 2025). "As RAB3B regulates chordoma tumorigenicity and mTORC1/S6 signaling, we further explored whether it mediates the cancer stemness through S6." (PMID 40135815, 2025). "Moreover, overexpression and knockout of RAB3B also validated its roles in regulating chordoma stemness markers." (PMID 40135815, 2025). "Based on functional experiments and clinical data, mTORC1‐targeted therapy could be regarded as a potential therapeutic modality for chordoma, especially with aberrant hyperactivation of RAB3B/p‐S6." (PMID 40135815, 2025). "Taken together, these results indicate that RAB3B may serve as a pivotal oncogenic driver of chordoma." (PMID 40135815, 2025). "Notably, RAB3B ablation attenuated the chordoma cell stemness and malignant biological properties in vivo and in vitro." (PMID 40135815, 2025). "Moreover, our results indicate RAB3B/p‐S6 as a candidate response predictor of chordoma patients to mTORC1‐targeted therapies." (PMID 40135815, 2025). "Thus, high expression of RAB3B may serve as a potential indicator for the application of mTORC1 inhibitors in chordoma patients." (PMID 40135815, 2025). "Although our results revealed that mTORC1‐targeted therapy may serve as a potential option for chordoma with abnormal RAB3B/p‐S6 hyperactivation, the immunosuppressive properties remain a potential obstacle to the clinical application of mTORC1 inhibition in cancer therapy." (PMID 40135815, 2025). "As RAB3B‐induced S6 phosphorylation could be inhibited by dactolisib and rapamycin, we tested the predictive value of RAB3B in the dactolisib or rapamycin treatment for chordoma." (PMID 40135815, 2025). "To confirm the RAB3B expression in chordoma, we analyzed the transcriptomic data and tissue microarray (TMA) of chordoma (n = 120) and NP (n = 30)." (PMID 40135815, 2025). "To explore the potential tumorigenic regulators in chordoma, we identified the overlapped markers between DEGs and DEPs, in which RAB3B ranked first in oncogenic regulators and NF1A served as an important chordoma suppressor." (PMID 40135815, 2025). "The assay for transposase‐accessible chromatin with high throughput sequencing (ATAC‐seq) data of chordoma cell lines (CH22, U‐CH2, and MUG‐Chor1) and NP cells were used to identify the chromatin accessibility and transcription factor occupancy of RAB3B." (PMID 40135815, 2025). "Knockout of RAB3B significantly impaired the cell proliferation of CH22 in a time‐dependent manner, which was further validated in RAB3B siRNA‐treated chordoma cells (CH22, U‐CH1, U‐CH2, and MUG‐Chor1)." (PMID 40135815, 2025).
chordoma (continued). "In addition to the well‐known chordoma biomarkers (LGALS3 and TBXT), the heatmap also revealed IGKV2, IL13RA2, RAB3B, and MAPK3 highly expressed in chordoma." (PMID 40135815, 2025). "ACAN, CA12, and RAB3B were differentially expressed in chordoma versus normal tissue and mesenchymal tumors but not IVD." (PMID 21253487, 2010). "Rapamycin decreased the chordoma cell growth in CH22Flag‐RAB3B and CH22WT, but not CH22sgRAB3B." (PMID 40135815, 2025).
colon cancer (2 papers, 2017 to 2024). "In two colon cancer cell lines, we observed upregulation of other exocytic RABs including RAB3B, RAB26, and RAB27A as a result of RAB3C overexpression." (PMID 28784136, 2017).
lung adenocarcinoma (2 papers, 2024). A carcinoma that arises from the lung and is characterized by the presence of malignant glandular epithelial cells. "We show that Rab3B is differentially expressed between lung adenocarcinoma and adjacent normal tissues and induced upon LKB1 deficiency." (PMID 38834947, 2024). "Rab3B upregulation is associated with poor prognosis and promotes aggressive phenotype in lung adenocarcinoma." (PMID 38834947, 2024). "Taken together, our work indicates that Rab3B is upregulated in LKB1-deficient lung adenocarcinoma cells and drives lung adenocarcinoma progression through interaction with and stabilization of DDX6 protein." (PMID 38834947, 2024). "In this article, we reveal the induction of Rab3B in lung adenocarcinoma cells upon LKB1 deficiency." (PMID 38834947, 2024). "Upregulation of Rab3B was significantly associated with lymph node metastasis, advanced tumor stage, and reduced overall survival in lung adenocarcinoma patients." (PMID 38834947, 2024). "Among them, Rab3B mRNA expression was significantly associated with overall survival of lung adenocarcinoma patients (P = 0.0014), which was determined based on Kaplan–Meier plotter." (PMID 38834947, 2024). "Elevated Rab3B expression is associated with lymph node metastasis, advanced tumor stage, and shorter overall survival in patient with lung adenocarcinoma." (PMID 38834947, 2024). "Taken together, high Rab3B expression is associated with poor prognosis of lung adenocarcinoma." (PMID 38834947, 2024). "In a mouse xenograft model, Rab3B depletion restrained and Rab3B overexpression augmented the growth of lung adenocarcinoma tumors." (PMID 38834947, 2024). "Knockdown of Rab3B suppressed and overexpression of Rab3B promoted the proliferation, colony formation, and migration of lung adenocarcinoma cells in vitro." (PMID 38834947, 2024). "Most importantly, ectopic expression of DDX6 can partially rescue the proliferation, colony formation, and migration potential in Rab3B-depleted lung adenocarcinoma cells." (PMID 38834947, 2024). "We found that Rab3B H-scores were significantly higher in lung adenocarcinoma than those in adjacent lung tissues." (PMID 38834947, 2024). "Rab3B was upregulated in LKB1-depleted lung adenocarcinoma cells and suppressed by LKB1 overexpression." (PMID 38834947, 2024). "Consistently, our data demonstrate that Rab3B can promote the proliferation, colony formation, and migration of lung adenocarcinoma cells." (PMID 38834947, 2024). "Rab3B upregulation is correlated with advanced disease and poor prognosis in patients with lung adenocarcinoma." (PMID 38834947, 2024). "Most importantly, lung adenocarcinoma patients with high Rab3B expression in tumors had significantly shorter overall survival than those with low Rab3B expression (P = 0.0003)." (PMID 38834947, 2024). "Our data show that Rab3B expression is enhanced in lung adenocarcinoma relative to adjacent normal tissues." (PMID 38834947, 2024). "Immunohistochemistry revealed the elevated expression of Rab3B in lung adenocarcinomas relative to adjacent normal tissues." (PMID 38834947, 2024). "Additionally, DDX6 overexpression partially rescued the aggressive phenotype of Rab3B-depleted lung adenocarcinoma cells." (PMID 38834947, 2024). "Interestingly, we demonstrate that DDX6-depleted lung adenocarcinoma cells recapitulate the phenotype of Rab3B-depleted counterparts." (PMID 38834947, 2024). "Rab3B-meidated aggressive phenotype in lung adenocarcinoma cells is impaired when DDX6 is silenced." (PMID 38834947, 2024). "Here, we provide first evidence for the oncogenic function of Rab3B in lung adenocarcinoma." (PMID 38834947, 2024). "We also clarify how Rab3B fuels lung adenocarcinoma progression." (PMID 38834947, 2024). "DDX6 knockdown phenocopied the effects of Rab3B depletion on lung adenocarcinoma cells." (PMID 38834947, 2024). "In this study, we show that there is an interaction between Rab3B and DDX6 in lung adenocarcinoma cells." (PMID 38834947, 2024).